SCIN (scinderin)
Diseases named in the same sentence as SCIN in open-access papers (continued):
Sharing a sentence is not in itself a finding about the gene and the disease.
lymph node metastasis (3 papers, 2019 to 2024). "The “TCGA analysis” module of UALCAN was used to find that SCIN expression was closely associated with lymph node metastasis of PRAD (N0 vs. Normal: P = 2.05e-08,N1 vs. N0: P = 2.50e-02, N1 vs. Normal: P = 3.51e-02)." (PMID 39108273, 2024). "Further analysis revealed that the SCIN transcription level was correlated with lymph node metastasis of PRAD, and was related to the pathological stage of KIRC and LIHC." (PMID 39108273, 2024). "The results showed that reduced Gelsolin and increased Scinderin expression were related to lymph node metastasis." (PMID 32636728, 2020). "Similarly, the previous evidence showed that SCIN expression was correlated with lymph node metastasis and pathological stage of CRC." (PMID 39108273, 2024). "In addition to SCIN expression, univariate analysis also identified poor tumor differentiation, depth of invasion infiltration (T3-4), lymph node metastasis, and distant metastasis (SLM and MLM) as significantly associated with poor OS." (PMID 31736743, 2019). "A sharp increased expression of Scinderin and a reduction of expression of Gelsolin was more significant in samples with positive lymph node metastasis (60.97 %) in contrast with samples with no lymph node metastasis (39.02 %)." (PMID 32636728, 2020). "We found high SCIN expression was related to the depth of invasion and lymph node metastasis (P < 0.05), but was not related to age, gender, tumor location, tumor size, gross appearance, histological type, and tumor differentiation (P > 0.05)." (PMID 31736743, 2019).
bladder cancer (2 papers, 2019 to 2021). "Human bladder cancer cell line HT1376 with high SCIN expression showed significant cisplatin resistant and SCIN mRNA knockdown reduced cell proliferation with mitochondria-mediated apoptosis." (PMID 34405002, 2021).
hepatocellular carcinoma (2 papers, 2022 to 2024). A malignant tumor that arises from hepatocytes. "To further dissect the role of SCIN in LIHC, we knocked down the SCIN expression in hepatocellular carcinoma cells." (PMID 39108273, 2024). "Aberrant expression of SCIN promoted hepatocellular carcinoma cells proliferation partly in vivo and in vitro, and SCIN silence prolonged the OS in animal models to some extent." (PMID 39108273, 2024). "The overexpression of SCIN was determined in hepatocellular carcinoma cell lines, compared with normal control cells." (PMID 39108273, 2024). "Our experiments in vitro determined the abnormal upregulation of SCIN in hepatocellular carcinoma cells." (PMID 39108273, 2024). "As a function effector of tumor metastasis suppressor factor (BRMS1), SCIN plays a regulatory role in the apoptosis of hepatocellular carcinoma cells." (PMID 39108273, 2024). "Results indicated that SCIN knockdown suppressed the proliferative ability of hepatocellular carcinoma cells." (PMID 39108273, 2024). "Collectively, SCIN knockdown could inhibit the hepatocellular carcinoma growth and enhance survival rate of tumor bearing mice." (PMID 39108273, 2024).
liver cancer (2 papers, 2024). An epithelial or non-epithelial malignant neoplasm that arises from the liver. "Together, we demonstrate that SCIN plays an important role in mediating the growth process of liver cancer." (PMID 39108273, 2024). "Based on Kaplan-Meier plotter, high expression of SCIN was correlated with poor prognosis of thymoma (P = 0.043) and liver cancer (P = 1e-4)." (PMID 39108273, 2024). "Later, the Venn diagram revealed that SCIN could play a role in liver cancer through ABCC 1, CAPG and PRNP, and the relationship between the three genes and SCIN in liver cancer was verified in GSCA database." (PMID 39108273, 2024). "First, the aberrant expression of SCIN in liver cancer were not validated in a large number of clinical samples." (PMID 39108273, 2024).
ovarian carcinoma (2 papers, 2020 to 2024). A malignant neoplasm originating from the surface ovarian epithelium. "On the contrary, the high expression of SCIN was associated with high OS rate in kidney renal papillary cell carcinoma (P = 0.0028) and ovarian cancer (P = 0.036)." (PMID 39108273, 2024).
Arthritis (1 paper, 2022). Inflammation of a joint. "Given the many members of the gelsolin family involved, such as scinderin (adseverin) as well, and their seemingly opposing roles in arthritis, further research on this topic is needed to understand the involvement of gelsolin in arthritis." (PMID 35327525, 2022).
bacteremia (1 paper, 2016). "Importantly, in our study, i.v. vaccinated mice produced high levels of antibodies against many of the antigens that also elicit IgG binding in bacteremia patients, including SCIN, LukF, Plc, GlpQ, SACOL0985 (EapH2), and the immunodominant antigen IsaA." (PMID 27103319, 2016).
cognitive decline (1 paper, 2023). "Finally, SCIN which encodes an actin-binding protein has variants that associate with inflammation markers and rate of cognitive decline in ADs." (PMID 36609403, 2023).
colon cancer (1 paper, 2023). "It was noted that the amount of β-catenin in cells went up with the increased expression of SCIN, and that SCIN expression is high in a variety of samples from patients with colon cancer, which also contained elevated levels of β-catenin." (PMID 37232717, 2023).
COVID-19 (1 paper, 2023). A disease caused by infection with severe acute respiratory syndrome coronavirus 2. "Antibodies against SCIN showed no change over time after COVID-19 vaccination." (PMID 38006026, 2023).
gastric tumor (1 paper, 2020). "In line with previous studies, the present study showed significant over-expression of Scinderin in gastric tumor tissues compared to the adjacent normal tissue." (PMID 32636728, 2020). "The expression levels of two important actin-binding proteins, Gelsolin and Scinderin, were studied in gastric tumor and the adjacent normal tissue in this study." (PMID 32636728, 2020).
Lewy Body disease (1 paper, 2023). "Notably, upregulated expression of SCIN was identified as part of a pan-neurodegenerative gene signature across AD, Lewy Body disease, and ALS-FTD." (PMID 36609403, 2023).
sarcoma (1 paper, 2024). A usually aggressive malignant neoplasm of the soft tissue or bone. "Further, our results indicated that SCIN mutations significantly impacted OS (P = 6.013e-03), PFS (P = 0.0121), and DSS (P = 1.248e-03) of Sarcoma patients." (PMID 39108273, 2024).
triple-negative breast carcinoma (1 paper, 2023). An invasive breast carcinoma which is negative for expression of estrogen receptor (ER), progesterone receptor (PR), and human epidermal growth factor receptor 2 (HER2). "SCIN was identified as a novel transcriptional target of RSRC2 in triple-negative breast cancer cells." (PMID 38201443, 2023).
tumor (16 papers, 2011 to 2025). "Results showed that SCIN expression was significantly associated with tumor stage (P=0.02578) and pathologic T staging (P=0.0435)." (PMID 39108273, 2024). "Based on results, a significant association was observed between tumor size and Scinderin expression level." (PMID 32636728, 2020). "Similar results were also obtained in this study, and a significant association was observed between tumor size and Scinderin expression level." (PMID 32636728, 2020). "Given that SCIN knockdown reduced tumor cell proliferation, we next investigated whether the suppression of SCIN was associated with reduced tumor growth." (PMID 39108273, 2024). "RNA-Seq showed that among the DEGs in tumor versus distal ILC3s, many were associated with tumor development or inhibition; however, most of the DEGs were involved in tumor suppression, especially SCIN, which was upregulated in tumor ILC3s." (PMID 33708200, 2021). "Thus, genetic alteration of SCIN may affect substrates expressions, however the role of SCIN mutations in tumor tissues is rarely studied." (PMID 39108273, 2024). "Furthermore, the abnormal expression of SCIN exhibited a strong relationship with immune cell subtypes, immune checkpoint genes, tumor mutation burden, microsatellite instability, neoantigen, molecular subtypes, mismatch repair signatures and DNA methyl-transferase in different cancer types." (PMID 39108273, 2024). "Notably, significant functional differences are predicted between the long or short isoforms of TCF12, OSBPL1A, TRAK1, CHEK1, ANK3, LMO7 and SCIN indicating that the observed tumor associated changes in TSS usage probably have an impact on the growth properties of the neoplastic cells." (PMID 21999571, 2011). "In summary, we demonstrated that RSRC2 served as a tumor suppressor in TNBC through negatively regulating SCIN-mediated cell function." (PMID 38201443, 2023). "The downregulation of SCIN expression can make liver cancer cells sensitive to chemotherapy drugs, thus inhibiting tumor growth." (PMID 38201443, 2023). "In brief, SCIN was suggested as a potential prognostic marker and a therapeutic target for some tumors, but the role of SCIN in tumor development and progression are controversial among different research projects." (PMID 36291348, 2022). "Although the correlation between the SCIN expression and cancer progression has been revealed for a long time, multiple studies showed the role of SCIN in tumor development was controversial among different investigators." (PMID 36291348, 2022). "In this study, significant down-regulation of Gelsolin (p=0.001) and over-expression of Scinderin (p=0.001) were observed in tumor tissues compared to the adjacent normal tissues." (PMID 32636728, 2020). "Consistently, SCIN overexpression protected cells from apoptosis, promoted xenografted tumor cell growth." (PMID 31736743, 2019). "The results showed that the decreased expression of SCIN dramatically reduced the growth of tumours in vivo as indicated by the tumour weight and volume." (PMID 29744289, 2018). "We have previously reported that increased EPHRIN-A1 and SCINDERIN expression in tumor cells conferred resistance to CD8+ T cell-mediated lysis by a mechanism linked to actin cytoskeleton remodeling." (PMID 24330498, 2013). "Our group has previously shown that EPHRIN-A1 and SCINDERIN expression by tumor cells rendered them resistant to cytotoxic T lymphocyte-mediated lysis." (PMID 24330498, 2013). "Consequently, clinicopathological characteristics and the expression levels of GSN, SCIN, CAPG, VILL, VIL1, SVIL, and FLII were found to be closely associated with tumor stages in EC." (PMID 39964147, 2025). "The commonly overexpressed genes that may be involved in tumor secretion include SCIN (scinderin) and CPNE4 (calcium-dependent phospholipid-binding protein)." (PMID 40002253, 2025).
tumor (continued). "Experiments in vitro and in vivo suggested the knockdown of SCIN could suppress tumor cell proliferation and improve the survival rate partly in animal models." (PMID 39108273, 2024). "SCIN may promote tumor occurrence and subsequent progression of various cancers though DNA methylation, mutation, and tumor immune cell infiltration." (PMID 39108273, 2024). "It means that SCIN might regulate and recruit immune cells to promote or inhibit the progression of cancers, and thus play a complexly regulative role in tumor progression." (PMID 39108273, 2024). "The role of SCIN in various tumor molecular subtypes was investigated by the TISIDB database." (PMID 39108273, 2024). "In the TISIDB database, heatmaps showed the correlations between SCIN expression and tumor-infiltrating lymphocytes (TILs), chemokines, chemokine receptors, immuneinhibitors, immunostimulators, and a major histocompatibility complex (MHC) molecule in pan cancer." (PMID 36291348, 2022). "In contrast to Scinderin, no signification association was found between Gelsolin expression level and tumor size." (PMID 32636728, 2020). "Recent studies suggest SCIN may be involved in the regulation of tumor development." (PMID 36291348, 2022). "Moreover, the EGFR protein level was downregulated by silencing of SCIN in all tumour tissues." (PMID 29744289, 2018). "Thus, SCIN may affect anti-tumor immunity by regulating tumor microenvironment." (PMID 39108273, 2024). "In summary, our study reveals that RSRC2 acts as a tumor suppressor in TNBC development and progression through negatively regulating SCIN-mediated cell function, thus providing a potential target for TNBC treatment." (PMID 38201443, 2023). "We used different transcriptional expressions of SCIN in tumor and normal tissues using GEPIA and we found that SCIN expression was significantly differentially expressed in some cancers, especially in the LGG and GBM." (PMID 36291348, 2022). "Research has shown that the capping protein scinderin (SCIN) regulates actin and then participates in the migration of tumor cells." (PMID 29618386, 2018). "We investigated the putative prognosis value of two molecules involved in tumor cell resistance to CD8+ T cell-mediated lysis, EPHRIN-A1 and SCINDERIN." (PMID 24330498, 2013). "Our group showed that SCINDERIN and EPHRIN-A1 are directly responsible for conferring resistance to tumor cells from CD8+ T cell attack." (PMID 24330498, 2013). "Although the specific role of SCIN has been identified in single tumor type, the detailed role of SCIN and related mechanism in pan-cancer has not been elucidated." (PMID 39108273, 2024). "Meanwhile, the expression of Gelsolin was significantly lower and the expression of Scinderin was significantly higher in tumor tissues compared to non-tumor tissues obtained from the same patients in this study." (PMID 32636728, 2020). "In addition, we monitored the HLA-class I expression by tumor cells and the presence of tumor-infiltrating CD8+ T cells to evaluate a putative correlation between these factors and the survival prognosis by themselves or related to EPHRIN-A1 and SCINDERIN expression." (PMID 24330498, 2013). "No prognostic value could be observed when CD8+ T cell tumor infiltration was analyzed combined with EPHRIN-A1, SCINDERIN or HLA class I expression." (PMID 24330498, 2013).
cancer (14 papers, 2011 to 2025). A tumor composed of atypical neoplastic, often pleomorphic cells that invade other tissues. "For several remaining top genes, functional validation pinpointed a causal role in carcinogenesis, but in specific cancers other than KIRC (SCIN, HAGLR, GSTP1)." (PMID 41188181, 2025). "In the present study, we investigated the role of SCIN in the regulation of cancer cell proliferation and its underlying mechanism by analysing related signalling pathway molecules." (PMID 29744289, 2018). "In addition, SCIN, a gene strongly associated with proliferation, migration and differentiation in cancer, exhibited with a (log2fold change of 7.52) high level of significance." (PMID 40946111, 2025). "Furthermore, Gelsolin and Scinderin expression was assessed in different grades and stages to determine the association of this gene with cancer progression." (PMID 32636728, 2020). "Furthermore, Gelsolin and Scinderin expressions were assessed in different grades and stages to determine the association of this gene with cancer progression." (PMID 32636728, 2020). "We confirmed the differential upregulation of previously known genes in such as SCIN, CALD1 and MCAM, which have been associated with aggressive, basal-like phenotype and in acquired drug resistance in cancer." (PMID 40946111, 2025). "Above all, our study systematically and comprehensively summarized the role of SCIN in pan-cancer, especially in LIHC." (PMID 39108273, 2024). "Meanwhile, a set of factors, such as expression level, survival status, DNA mutation and genomic methylation were considered to explore the potential role of SCIN in the mechanism of the tumorigenesis of various cancers." (PMID 39108273, 2024). "Pan-cancer differential expression analysis suggested SCIN expression was significantly increased in CHOL, LIHC, LUAD, and PRAD, but decreased in COAD, HNSC, KIRC, LUSC, and STAD compared with adjacent normal tissues." (PMID 39108273, 2024). "Secondly, using the Sangerbox database for further analysis, it was found that SCIN expression was related to the infiltration of 28 subtypes of immune cells in 24 cancers." (PMID 39108273, 2024). "Our research provides novel insights into the mechanism of SCIN expression in pan-cancer and improve the possibility of the SCIN target therapy in LIHC." (PMID 39108273, 2024). "Numerous studies strongly suggested that SCIN was highly expressed in a series of cancers, and exerted promising prognostic value for pan-cancer." (PMID 39108273, 2024). "SCIN is involved in cytoskeletal remodeling and the silencing of SCIN in cancer cells inhibits cell proliferation." (PMID 34445242, 2021). "Although the role of SCIN in cancer has been reported before, the correlation between miR-301a-5p and SCIN are unclear." (PMID 34405002, 2021). "Recently, studies found that SCIN functioning in the development and progression of some human cancers." (PMID 31736743, 2019). "So, we used DLD-1 and SW480 cell lines to study the biological function of SCIN in cancer cell growth." (PMID 31736743, 2019). "Whereas the prognostic value of EPHRIN-A1 expression in cancer has already been studied, the role of SCINDERIN presence remains to be established." (PMID 24330498, 2013). "Significantly differential expression of SCIN was found in nine types of cancers, including LIHC." (PMID 39108273, 2024). "Taken together, SCIN plays an important role in the recurrence and development of cancers." (PMID 39108273, 2024). "Next, the role of SCIN in human cancer immunity subtypes was dissected based on TISIDB database." (PMID 39108273, 2024). "This study reveals SCIN may be a promising biomarker for prognosis and treatment in certain cancers, especially in LIHC." (PMID 39108273, 2024). "Secondly, our study did not explore the detailed mechanisms underlying the role of SCIN involved in cancer development." (PMID 39108273, 2024). "First, to identify SCIN expression in human cancers, we carried out GEPIA." (PMID 36291348, 2022).
cancer (continued). "It has been suggested that Scinderin silencing could decrease cells proliferation, induce cancer cell cycle arrest and apoptosis." (PMID 32636728, 2020). "Thus, addressing the regulation or coordination of proteins in cell−motility machinery may provide novel insight to understand the dual role of SCIN in different cancer types." (PMID 39108273, 2024). "Therefore, SCIN is important for regulating cancer cell survival and migration." (PMID 34405002, 2021). "In addition, the deep investigation of the correlation between SCIN with its relevant genes and immune cell infiltration may shed light on understanding the dual role of SCIN in different cancer types and provide evidence of SCIN as the therapeutic target for cancers." (PMID 39108273, 2024). "A significant correlation was found between SCIN expression and CD4+T cells in 20 cancer types, B cells in 21 cancer types, CD8+T cells in 17 cancer types, macrophages in 18 cancer types, neutrophils in 21 cancer types, and dendritic cells in 25 cancer types." (PMID 39108273, 2024). "SCIN, LRP1B, CPNE3, TICRR, and PPP1R7 are connected to cancer cell invasion, migration, proliferation, and apoptosis." (PMID 37628788, 2023). "We previously showed that scinderin (SCIN), an important regulator of F‐actin organisation, is highly expressed in poorly differentiated cancer tissues." (PMID 29744289, 2018).
infection (3 papers, 2019 to 2024). The state of being infected such as from the introduction of a foreign agent such as serum, vaccine, antigenic substance or organism. "According to available studies, SCIN and CHIPS proteins are secreted most abundantly during the S. aureus exponential growth phase, during early stages of infection." (PMID 39200030, 2024). "Analysis of the expression profiles in our study revealed that miR-449a and miR-449b were highly expressed at the early stage of infection, whereas the expression of their target genes L1CAM, MYO3B, SCIN, and STMN1 decreased." (PMID 38178220, 2024).